XRCC1 (X-ray repair cross complementing 1)
Description:
Scaffold protein involved in DNA single-strand break repair by mediating the assembly of DNA break repair protein complexes. Negatively regulates ADP-ribosyltransferase activity of PARP1 during base-excision repair in order to prevent excessive PARP1 activity. Recognizes and binds poly-ADP-ribose chains: specifically binds auto-poly-ADP-ribosylated PARP1, limiting its activity.
Synonyms: RCC; SCAR26
Tractability: PROTAC: UniProt records ubiquitination sites on it; ubiquitination databases record sites on it; its protein half-life has been measured.
Safety:
Unwanted effects reported when the protein is acted on. In parentheses: how it was acted on, where the effect was seen, and who reports it.
nausea (source: ClinPGx)
severe neutropenia (source: ClinPGx)
survival (source: ClinPGx)
Gene: Protein-coding gene on chromosome 19 (43,543,306 to 43,580,473, reverse strand). Ensembl gene ENSG00000073050.
Subcellular location: Nucleus; Chromosome
Subcellular location (Human Protein Atlas): Nucleoplasm
Pathways (Reactome):
DNA Repair: APEX1-Independent Resolution of AP Sites via the Single Nucleotide Replacement Pathway; Gap-filling DNA repair synthesis and ligation in GG-NER; Gap-filling DNA repair synthesis and ligation in TC-NER; HDR through MMEJ (alt-NHEJ); Resolution of AP sites via the single-nucleotide replacement pathway
Gene Ontology:
Molecular function: ADP-D-ribose modification-dependent protein binding; enzyme binding; oxidized DNA binding; poly-ADP-D-ribose binding; protein binding; single-strand break-containing DNA binding; 3' overhang single-stranded DNA endodeoxyribonuclease activity; damaged DNA binding
Biological process: base-excision repair; double-strand break repair; negative regulation of protein ADP-ribosylation; regulation of base-excision repair; response to hydroperoxide; single strand break repair; regulation of DNA repair; double-strand break repair via nonhomologous end joining; negative regulation of protection from non-homologous end joining at telomere; telomeric DNA-containing double minutes formation
Cellular component: chromatin; chromosome; nucleolus; nucleoplasm; nucleus; site of DNA damage; DNA ligase III-XRCC1 complex; chromosome, telomeric region; ERCC4-ERCC1 complex
Genetic constraint (gnomAD): Loss-of-function variants: 52 observed, 84.74 expected, observed/expected ratio (o/e) 0.61, 90% interval 0.49 to 0.77. The upper end of that interval is the gene's LOEUF score, 0.77, which puts it in group 3 of 6, group 1 being the genes least tolerant of losing a copy. Missense variants: 793 observed, 838.38 expected, observed/expected ratio (o/e) 0.95, 90% interval 0.89 to 1. Synonymous variants: 281 observed, 322.86 expected, observed/expected ratio (o/e) 0.87, 90% interval 0.79 to 0.96.
Homologues: Orthologues: chimpanzee XRCC1 (99% identical), macaque XRCC1 (97% identical), dog XRCC1 (89% identical), pig XRCC1 (88% identical), guinea pig XRCC1 (87% identical), rat Xrcc1 (86% identical), mouse Xrcc1 (86% identical), rabbit XRCC1 (77% identical), tropical clawed frog xrcc1 (55% identical), Drosophila melanogaster XRCC1 (28% identical). Paralogues in human: XNDC1N (11% identical).
Diseases named in the same sentence as XRCC1 in open-access papers:
XRCC1 is named in the same sentence as 219 diseases in open-access papers, as found by Europe PMC text mining. Sharing a sentence is not in itself a finding about the gene and the disease. The quoted sentences say what the papers report.
breast carcinoma (89 papers, 2005 to 2025). "For the XRCC1 (rs1799782) gene, both genotype comparisons (AA vs. AT and TT vs. AT) showed highly significant associations with breast cancer subtype." (PMID 40507526, 2025). "rs25487/XRCC1 has been linked to increased risks for various diseases, mainly cancers, including breast cancer in American populations and lung cancer in susceptible Chinese populations." (PMID 40724862, 2025). "In particular, expression changes in the critical scaffold protein X-ray cross complementing protein 1 (XRCC1) are associated with hypersensitivity to PARPi in cell models and breast cancer." (PMID 40271221, 2025). "XRCC1 is a well-known DNA repair gene, and deficiency of XRCC1 promotes an aggressive phenotype of breast cancer." (PMID 36142451, 2022). "We have recently shown that PARP inhibitors (Olaparib, Talazoparib) induce selective toxicity in XRCC1 deficient ovarian and breast cancer cells." (PMID 34373746, 2021). "The results indicate that the heterozygous genotype for the XRCC1 rs1799782 polymorphism in female patients is related to a higher susceptibility to breast cancer than in males [OR 3.627; 95% CI 1.577–8.341]." (PMID 33942220, 2021). "Other reports have associated the upregulation of XRCC1 with increased risk of breast cancer; poor survival across low and high-risk breast cancer subtypes; increased tumor aggressiveness; and resistance to cisplatin, PARP inhibitors, and ionizing radiation." (PMID 34067421, 2021). "XRCC1 gene polymorphisms have been reported to be involved in multiple cancers, including breast cancer, lung cancer, and pancreatic cancer, but the potential mechanisms have not been identified." (PMID 32258128, 2020). "This study demonstrated that XRCC1-Gln/Gln genotype of Arg399Gln polymorphism was strongly correlated with breast cancer." (PMID 30728902, 2019). "Several studies have noted deficiency in XRCC1 in breast cancers and proposed defects in BER as targets for therapeutic intervention." (PMID 31596905, 2019). "Single nucleotide polymorphisms in BER genes such as POL β, PARP1, and X-ray cross complementing protein 1 (XRCC1) are associated with increased risk of developing breast cancer." (PMID 31596905, 2019). "The Arg399Gln polymorphism of XRCC1 gene was selected on the basis of literature data, which are highly suggestive of its correlations with breast cancer development." (PMID 30728902, 2019). "Statistically significant correlations were identified between four single nucleotide polymorphisms and the breast cancer risk: XRCC1-Arg399Gln, hMSH2-Gly322Asp, XPD- Lys751Gln and RAD51--4719A/T." (PMID 30728902, 2019). "Duellet al. also reported a null association between XRCC1 rs1799782 G>A and breast cancer risk in a population-based case-control study in North Carolina." (PMID 30362960, 2018). "We postulate that loss of single-strand DNA repair capacity through XRCC1 deletion in breast cancers creates a dependency on nucleotide excision repair by ERCC4." (PMID 26781748, 2016). "Further investigation of genetic variants in XRCC1 is warranted since a prognostic role of XRCC1 for breast cancer survival has been reported for the XRCC1 rs25487 SNP, which causes an amino acid change." (PMID 26674097, 2015). "In the coding region of XRCC1, the nonsynonymous polymorphism, Arg399Gln, has caught much attention in breast cancer risk for years." (PMID 24489692, 2014). "In conclusion, this meta-analysis provided evidence that the XRCC1 Arg399Gln polymorphism was significantly associated with risk of breast cancer in the American population." (PMID 24489692, 2014). "In the literature, many reports confirm the significance of XRCC1-Arg194Trp polymorphism, regarding the risk of breast carcinoma." (PMID 24402573, 2014). "As expected, this meta-analysis provides an obvious evidence that the XRCC1 Arg399Gln polymorphism is significant associated with of breast cancer in the American population." (PMID 24489692, 2014).
breast carcinoma (continued). "This meta-analysis suggests the participation of XRCC1 Arg399Gln is a genetic susceptibility for hepatocellular cancer in Asians and breast cancer in Indians." (PMID 24205095, 2013). "Different ethnicities cancer susceptibility associated with the XRCC1 Arg399Gln polymorphisms was also observed in previous meta-analyses of lung cancer and breast cancer." (PMID 24205020, 2013). "In summary, this meta-analysis suggests the participation of XRCC1 Arg399Gln is a genetic susceptibility for hepatocellular cancer in Asians and breast cancer in Indians." (PMID 24205095, 2013). "For the population-based studies, the XRCC1 Arg399Gln polymorphism was associated with breast cancer and bladder cancer risk." (PMID 24205095, 2013). "Recently, meta-analysis studies have reported that XRCC1 Arg399Gln variant was associated with the risk of certain cancers, such as breast cancer, nasopharyngeal carcinoma, cervical carcinoma and glioma." (PMID 24205020, 2013). "A total of 57 breast cancer patients who underwent SSPBI were genotyped for SNPs (single nucleotide polymorphisms) in XRCC1, XRCC3, GST and RAD51 by Pyrosequencing technology." (PMID 22272830, 2012). "Despite the number of genetic epidemiology studies that have evaluated breast cancer risk in relation to XRCC1 genotype, few have focused on women at high risk due to family history." (PMID 20442803, 2010). "We used a family-based case-control study design to evaluate the association between XRCC1 polymorphisms and breast cancer risk." (PMID 20442803, 2010). "Our data suggests that the XRCC1 194W allele is associated with an increase in breast cancer risk, while XRCC1 399Q and 280H alleles are associated with a decrease in risk in women with a family history of breast cancer." (PMID 20442803, 2010). "In order to evaluate the possible contribution of the XRCC1 polymorphisms to breast cancer susceptibility, we analyzed the genotype distribution in a group of women with an FH of breast cancer." (PMID 21637676, 2009). "Further studies with larger samples are needed to elucidate the role of these XRCC1 gene variants in the genetic susceptibility to breast cancer." (PMID 21637676, 2009). "Women reporting only second-degree relatives affected by breast cancer showed a similar genotype distribution and allele frequencies for both XRCC1 variants compared to the control group." (PMID 21637676, 2009). "The distribution of XRCC1 polymorphisms was similar in both groups, although women with an FH of breast cancer showed a higher percentage of genotypes presenting the Trip allele (Arg/Trp + Trp/Trp) than the controls (19.3% and 13.3%, respectively)." (PMID 21637676, 2009). "In the present study, we estimated the frequencies of the XRCC1 gene polymorphisms Arg194Trp and Arg399Gln in healthy individuals and also in women at risk of breast cancer due to family history from Rio de Janeiro." (PMID 21637676, 2009). "When the present study subjects were stratified by stage of disease, the XRCC1-399 Gln allele posed an elevated risk for more advanced stage breast cancer." (PMID 16280050, 2005). "On the other hand, our findings are in contrast to a French study showing a 1.8-fold (95% CI 1.04–3.08) increase in breast cancer risk for the XRCC1-280 Arg/His genotype." (PMID 16280050, 2005). "In a recent study on breast cancer, the XRCC1-399 Gln allele was significantly associated with detectable PAH-adducts only in never smokers." (PMID 16280050, 2005). "Only one earlier study on breast cancer risk has reported a positive association between XRCC1-399 polymorphism and smoking, but in contrast to our study, the highest risk was seen for subjects who were homozygous for the XRCC1-399 Arg allele." (PMID 16280050, 2005). "In agreement with this, the frequency of the variant XRCC1-399 Gln allele was somewhat higher among the present cases compared to controls, leading to a tendency of increased breast cancer risk." (PMID 16280050, 2005).
breast carcinoma (continued). "Our findings are consistent with those from four previous studies of XRCC1 polymorphisms and breast cancer risk that reported an inverse association between the Trp194 carriers and breast cancer risk in mostly Caucasian and other ethnic populations." (PMID 16457697, 2005). "In our study, genetic variation in XRCC1 Arg399Gln was associated with breast cancer risk only among women with a history of smoking cigarettes." (PMID 16457697, 2005). "We examined the association between polymorphisms in XRCC1 and breast cancer in the American Cancer Society Cancer Prevention Study II (CPS-II) Nutrition Cohort, a large prospective study of cancer incidence in the USA." (PMID 16457697, 2005). "Some of these studies suggest that associations between XRCC1 polymorphisms and breast cancer risk are stronger in women who smoke or who have higher exposure to various antioxidants." (PMID 16457697, 2005). "Conditional logistic regression models examining XRCC1 polymorphisms and postmenopausal breast cancer stratified by smoking status." (PMID 16457697, 2005). "Previous studies that examined the relationship between other XRCC1 polymorphisms and breast cancer risk generally have been null." (PMID 16457697, 2005). "The XRCC1 gene p.Q399R pure mutation is a missense mutation caused by single-nucleotide polymorphism rs25487, which is associated with the risk of non-small-cell lung cancer, breast cancer, colorectal cancer, gastric cancer, and other types of tumors." (PMID 41256322, 2025). "Importantly, PD1+ or PDL1+ breast cancers with low XRCC1 were linked to aggressive cancers and reduced survival including in ER– breast cancers in that study." (PMID 38134458, 2023). "Recently, the survival association of XRCC1 SNPs and XRCC1 protein expression have been reported in various human malignant tumors such as thyroid cancer, lung cancer, breast cancer, gallbladder cancer, and hepatocellular carcinoma." (PMID 36685969, 2022). "Moreover, XRCC1 is closely related to side effects caused by radiotherapy in breast cancer patients." (PMID 34766149, 2021). "We therefore concluded that XRCC1 deficiency could be exploited for a potential synthetic lethality for HRAS in breast cancer." (PMID 32101536, 2020). "XRCC1 (encoding X-ray repair cross-complementing protein 1), a key component of DNA base excision repair, single strand break repair, and backup non-homologous end-joining pathway, was reported to be involved in breast cancer." (PMID 32101536, 2020). "Furthermore, the OGG1 and XRCC1 rs25487 polymorphisms were nominally associated with PgR, Her2 status and with sporadic breast cancer, respectively." (PMID 32192442, 2020). "In addition, our analysis of data related to breast cancer patients harboring nonsynonymous somatic mutations in either gene of XRCC1-HRAS indicates poor survival rate compared with wild-type group (P = 0, log-rank test)." (PMID 32101536, 2020). "XRCC1 deficiency was reported to promote genomic instability and increase breast cancer risk." (PMID 32101536, 2020). "Moreover, low XRCC1 expression has recently been reported to impact prognosis in BRCA1-deficient breast cancers." (PMID 29568385, 2018). "Herein, we believed that it is essential to conduct an update comprehensive meta-analysis including studies published since 2001 to provide a more precise assessment of the association between the Arg399Gln in XRCC1 and breast cancer risk in the American population." (PMID 24489692, 2014). "This meta-analysis suggests that the XRCC1 Arg399Gln polymorphism may significantly contribute to susceptibility of breast cancer in the American population." (PMID 24489692, 2014). "The association of XRCC1 with breast cancer has been investigated in many other countries." (PMID 24489692, 2014).
breast carcinoma (continued). "We hypothesized a priori that the association between XRCC1 polymorphisms and breast cancer risk might be stronger in women who had experienced greater exposure to DNA-damaging agents, such as tobacco smoke." (PMID 16457697, 2005). "Our results support the hypothesis that genetic variation in XRCC1, particularly in Arg194Trp, may influence postmenopausal breast cancer risk." (PMID 16457697, 2005). "Results from this study support the hypothesis that genetic variation in XRCC1 may affect a woman's breast cancer risk, especially in women who have ever smoked cigarettes." (PMID 16457697, 2005). "Our results suggest that non-synonymous coding polymorphisms in XRCC1 may be associated with postmenopausal breast cancer risk, especially among women who have ever smoked." (PMID 16457697, 2005). "However, results of previous association studies of these two XRCC1 variants and breast cancer have been inconsistent." (PMID 16457697, 2005). "Although the association observed between XRCC1 polymorphisms and breast cancer risk among smokers in this study is interesting and adds support to the hypothesis, we cannot exclude chance as a possible explanation for the findings." (PMID 16457697, 2005). "We also examined whether factors associated with DNA damage, such as smoking and antioxidant intake, modified the association between XRCC1 polymorphisms and breast cancer." (PMID 16457697, 2005). "Given that low XRCC1 gene expression has also been shown to enhance the cytotoxic effects of PARPi in breast cancer cell lines, we hypothesized that XRCC1 deficiency could be a promising target for treatment with PARPi in PCa and mCRPC, especially for AA PCa patients." (PMID 40271221, 2025). "Although knocking out key BER factors such as Pol β and XRCC1 in mice often leads to embryonic lethality, cells of numerous different types of cancer tissues harbor mutated Pol β, and several XRCC1 polymorphisms have been associated with breast cancer or lung cancer in Asian patients." (PMID 38554113, 2024). "However, little is known about BER defects in breast cancer, particularly those linked to XRCC1." (PMID 31596905, 2019). "The XRCC1 rs1799782 TT genotype was found to be associated with an increased risk of lung, esophageal, and cervical cancer in a Chinese population, and the rs25487 AA genotype was linked to an increased risk of breast cancer among women and pancreatic cancer in a Chinese population." (PMID 26681190, 2015). "The results from our epidemiologic analysis suggest that the rare allele of XRCC1 R194W increases breast cancer risk, while the rare alleles of XRCC1 R280H and XRCC1 R399Q decrease risk among women from high-risk families, though these findings were only marginally significant with XRCC1 399Q." (PMID 20442803, 2010). "However, few studies have examined the relationship between XRCC1 polymorphisms and breast cancer risk in subgroups of the population that may experience higher levels of DNA damage, such as smokers." (PMID 16457697, 2005). "Polymorphisms in repair genes (BRCA1, BRCA2, CHEK2, XRCC1, XPD) can reduce DNA repair efficiency, leading to genomic instability and increased breast cancer risk." (PMID 40507526, 2025). "Most interestingly, XRCC1 depletion sensitizes ovarian and breast cancer preclinical models to PARPi." (PMID 40271221, 2025). "By impairing the repair of crucial DNA lesions, functional polymorphisms in XRCC1, XPD, and CHEK2 contribute to the development and severity of breast cancer." (PMID 40507526, 2025). "This preliminary study investigated the distribution and potential associations between three DNA repair gene polymorphisms—XRCC1 (rs1799782), CHEK2 (rs17879961), and XPD (rs238406)—in a cohort of female patients diagnosed with breast cancer." (PMID 40507526, 2025).